CASP1 (caspase 1)
Diseases named in the same sentence as CASP1 in open-access papers (continued):
Sharing a sentence is not in itself a finding about the gene and the disease.
viral infection (continued). "The silkworm response to viral infection has attracted extensive attention, and some host proteins such as caspase-1 and V-ATPase are reportedly involved in host resistance to viral infection." (PMID 28414724, 2017). "Increased expression of IL6 and CASP1 is known to be involved in the cellular response to viral infection." (PMID 26871479, 2016). "Upon viral infection, host intracellular inflammasomes sense the double stranded DNA derived from DNA viruses, and stimulate the activation of caspase-1 through the recruitment of procaspase-1 by CARD-containing proteins." (PMID 26047333, 2015). "Caspase-1 activation and IL-18 and IL-1β maturation are triggered by the assembly of these inflammasome protein complexes in response to some acute viral infections." (PMID 24788318, 2014). "Consistent with classical activation of the inflammasome by viral infection, significant levels of both IL-1β and IL-18 in their mature forms were detected in the supernatant of infected cells, and caspase-1 inhibition had an impact on this release." (PMID 23723976, 2013). "NALP3 inflammasome assembly, caspase-1 activation and subsequent IL-1β release can be triggered by a plethora of environmental insults, including viral infections." (PMID 23935506, 2013). "It was observed that a cohort given a yellow fever vaccine showed upregulation of caspase-1 and caspase-5." (PMID 24155744, 2013). "Furthermore, RIPK1 inhibition in IBV Conn A5968-infected cells enhanced caspase-1 activity, suggesting a potential crosstalk between RIPK1 and NLRP3 pathways in regulating caspase-1 activity, as described in other viral infection models." (PMID 40284946, 2025). "A greater number of genes are upregulated in DCs after MRV infection, many of which are involved in the innate immune response (i.e. Ifit1, Ifit3, Mx1, Gbp2, Oasl1, Isg15, Ccr1, Ifitm2, Oaxl2, Casp1, Casp4) that would be predicted in response to a viral infection." (PMID 38895117, 2024). "To determine how inflammasome activation impacts DENV pathogenesis upon viral infection, we crossed Casp1/11-/- or Nlrp3-/- separately with Ifnar-/- mice to generate Casp1/11-/ -x Ifnar-/- and Nlrp3-/-x Ifnar-/- double-deficient mice and infected them with DENV2 D220." (PMID 38662771, 2024). "Thus caspase-1 and IL-1β pathways appear to be central in affecting polyamine metabolism dependent immune-dysfunction during viral infections." (PMID 36693889, 2023). "IFI16 inflammasome is a large signaling platform activated by IFI16 in response to viral infection, which also contains the adapter protein ASC (apoptosis-associated speck-like protein containing a caspase recruitment domain) and effector enzyme pro-caspase-1." (PMID 35906635, 2022). "In particular, upon viral infection, ALR or NLR families, including NLRP1, NLRP2, NLRP3, and AIM2, detect pathogen-associated molecular patterns (PAMPs) and assemble an intracellular inflammasome complex by recruiting ASC and pro-caspase-1." (PMID 34360684, 2021). "Moreover, nuclear localization of caspase-1 and inflammasome components, and also formation of active nuclear inflammasomes in response to viral infections and TNF-α was previously demonstrated." (PMID 28153032, 2017). "During viral infection, viral DNA/RNA recognized by pattern recognition receptors (PRRs) in host cells can promote the formation of inflammasomes, resulting in the activation of caspase-1." (PMID 26334101, 2015). "We then determined caspase-1 activity during viral infection upon DPI treatment." (PMID 22393394, 2012). "Infection of THP-1 cells with vMyxM013-KO virus significantly increased IL-1β secretion within one hour, compared to control MYXV, indicating that the vMyxM013-KO virus was uniquely unable to block the inflammasome/caspase 1-mediated response to the virus infection." (PMID 19851467, 2009).
viral infection (continued). "Studies on pharmacological inhibition of various viral diseases have shown that inhibition of Caspase-1 could block the GSDMD-mediated cell pyroptosis process and reduce the expression levels of IL-1β and IL-18, leading to corresponding therapeutic effects on viral diseases." (PMID 38132483, 2023). "Nonetheless, whether caspase-1 and other inflammatory components in the nucleus play a significant role during the progression of inflammatory disorders other than during the viral infections and pharmacological interventions such as doxorubicin have not been studied." (PMID 27842563, 2016). "Viral infection of M1 macrophages upregulated the mRNA levels of NLRP3, caspase-1, and Gasdermin D (GSDMD)." (PMID 41305513, 2025). "Remarkably, the NLRP3 inflammasome inhibitor MCC950 significantly reduced caspase-1 activity, aligning with previous studies that have demonstrated a central role for NLRP3 in inflammasome activation during viral infections." (PMID 40284946, 2025). "During viral infection, a complex cascade involving NLRP3, ASC and Pro-caspase-1 forms to process the precursors of IL-1β and IL-18 into active forms." (PMID 39038050, 2024). "PGAM5 regulates the activity of inflammasome and caspase 1 in BMDMs and contributes to IFN-β production in response to viral infection by promoting the TBK1 (TANK-binding kinase 1)/IFN regulatory factor 3 (IRF3) signaling pathway." (PMID 37771598, 2023). "On day 5 of p.i., the expression of caspase-1 was significantly decreased at both mRNA and protein levels, when mice treated with Ac-YVAD-CMK after viral infection for once or three times compared with that of the infected mice without Ac-YVAD-CMK treatment." (PMID 29440739, 2018). "We next determined the efficacy of the well-characterized caspase-1-specific antagonist Z-YVAD-FMK in preventing bite enhancement of virus infection." (PMID 27332734, 2016). "Sendai virus and influenza A virus were the earliest viruses to be studied for their ability to activate caspase-1 through NLRP3, thereby promoting the production of IL-1β and IL-18, which provided evidence for the involvement of the NLRP3 inflammasome in the viral infection response." (PMID 40906404, 2025). "Furthermore, we observed a positive correlation between the mRNA transcription levels of NLRP3, caspase-1, and GSDMD and the duration of viral infection." (PMID 40284982, 2025). "When the expression of caspase-1 was inhibited by caspase-1 siRNA, the infection of CVB3 or EV71 failed to elicit the elevated maturation of both IL-1β and IL-18, indicating that the maturation of both cytokines depends on caspase-1 during viral infection." (PMID 29440739, 2018). "Expression of both CASP1 and IL6 genes could be induced not only by viral infection directly but also by GPR160 siRNAs in a virus-free transient transfection system." (PMID 26871479, 2016). "However, unlike in viral infection, deletion of ZBP1 in our fungal model did not result in a complete loss of CASP1 activation, GSDMD cleavage, or apoptotic protein (CASP8, CASP3, and CASP7) activation." (PMID 33109609, 2020). "We demonstrated that viral infection failed to induce the elevation of the mature pro-inflammatory cytokines when the expression of caspase-1 was inhibited, indicating that caspase-1 plays an essential role in the pyroptosis elicited by the infection of CVB3 or EV71." (PMID 29440739, 2018).
breast cancer (66 papers, 2008 to 2025). A primary or metastatic malignant neoplasm involving the breast. "In a range of cancers, including colorectal and breast cancer, the activation of Caspase-1 has been linked to inflammatory responses and a less favorable prognosis." (PMID 40008397, 2025). "Further analysis showed that high levels of CASP1 expression are associated with a poor prognosis in breast cancer patients and play a large role in tumor cell invasion." (PMID 40806590, 2025). "The association between tumor cell caspase-1 and the tumor immune phenotype was explored in 24 primary breast cancers (12 ER+ and 12 triple negative) using multiplex IHC." (PMID 39353903, 2024). "In ovarian cancer cells with the 185delAG founder mutation in the breast cancer susceptibility gene 1, there was an increase in active IL‐1 and elevation in caspase 1 cleavage mediated by inflammasome." (PMID 37752941, 2023). "Through searching for the NCBI GEO dataset, the expression of NLRP3, PYCARD, CASP1, and IL-1β genes in the tumor-associated stroma of breast cancer patients were found to be increased with the pathological stage when compared with normal breast stroma." (PMID 38031068, 2023). "Moving on, caspase-1 mRNA levels were significantly decreased in the breast cancer tissues of patients, and loss of caspase-1 was associated with prostate and CRC tumorigenesis." (PMID 34429144, 2021). "We investigated the association of the expression of caspase-1 in the primary tumor and the prognosis of patients with breast cancer in a clinical database, cBioPortal." (PMID 30042341, 2018). "Given that decreased neovascularisation exerts antitumoural effects, the antiangiogenetic effect of this adipocytokine mediated by CASP1 upregulation might be another mechanism underlying the inverse association between adiponectin serum levels and breast cancer risk." (PMID 18827813, 2008). "Mitoxantrone 14, a fused polycyclic aryl compound, induces pyroptosis in breast cancer cells through the activation of caspase-1 and caspase-3, leading to GSDME activation." (PMID 39316325, 2025). "Song and colleagues, based on a bioinformatics analysis of available statistical data from the Breast Cancer Gene-Expression Miner database, showed a high mean level of expression of the CASP1 gene in TNBC patients." (PMID 40806590, 2025). "DHA 1 is a conjugated polyene fatty acid that has demonstrated its pyroptotic action on breast cancer cells through caspase-1/GSDMD activation." (PMID 39316325, 2025). "We discovered that SNRPE targeting enhanced ROS generation and induced caspase-1/GSDMD-mediated pyroptosis in mammary carcinoma cells." (PMID 40386046, 2025). "The property of tumor cells, especially this type of aggressive breast cancer cells, to produce pro-inflammatory mediators was highlighted by the statistically increased profile of caspase-1 in untreated MDA-MB-231 cells compared to MCF-12A cells (p < 0.01)." (PMID 39433537, 2024). "Our previous study showed that VX765, an agent that blocks NLRP3-dependent cytokine release by suppressing caspase-1, increased cell proliferation in epithelial cancer cells, such as prostate, lung, and breast cancers." (PMID 38543085, 2024). "ERα knockdown (KD) in luminal breast cancer cells resulted in increased binding of ETS1 to the caspase-1 promoter, while ERα over-expression in TNBC displaced ETS1 binding." (PMID 39353903, 2024). "In triple-negative and basal-like breast cancer cells caspase-1 is activated within the inflammasome, a complex formed by the assembly of caspase-1, Nod-like proteins (NALP), and ASC." (PMID 39625520, 2024). "Our previous findings showed that VX765, a caspase-1 inhibitor, induces cancer cell proliferation and angiogenesis in neuroblastoma, glioblastoma, lung, prostate, and breast cancer cells." (PMID 38543085, 2024).
breast cancer (continued). "The activation of this complex determines caspase-1 maturation and activation of IL-1β and IL-18 which contribute to host-defense mechanism, inflammatory responses elaboration and breast cancer development." (PMID 39433537, 2024). "For example, cisplatin has been demonstrated to be involved in NLRP3/caspase-1/GSDMD pyroptosis pathway in breast cancer cells." (PMID 36932407, 2023). "Docosahexaenoic acid (DHA) causes an increase in caspase-1 and GSDMD activity in breast cancer cells, triggering pyroptosis and inhibiting breast cancer growth." (PMID 37542283, 2023). "Caspase-1 in parenchymal cells of the tumor was negatively correlated with tumor progression, and upregulation of IL-18 in immune-stromal cells of breast cancer tissues is a potential immunotherapy target and a promising prognostic biomarker in this study." (PMID 38031068, 2023). "Caspase-1/tPPARγ/medium-chain acyl-CoA dehydrogenase (MCAD) signaling axis plays an important role in the differentiation of TAMs isolated from mouse breast cancer tissues." (PMID 37004014, 2023). "The M. buxifolia persuaded the upregulation of proapoptotic marker genes (Caspase-1, -3, -7 and -9) and the downregulation of the WNT pathway associated genes WNT-3a and β-catenin, which caused apoptotic cell death in human breast cancer cells." (PMID 36904007, 2023). "RIG-I agonists can activate the intrinsic immune effector RIG-I in breast cancer cells, increase the immunogenicity of the tumor, activate caspase-1 cleavage of GSDMD in vitro, and are a viable approach for the treatment of breast cancer." (PMID 37542283, 2023). "According to these findings, using NLRP3 and caspase-1 (MCC950 or Ac-YVAD-cmk) inhibitors to treat breast cancer cells can slow their proliferation." (PMID 37715239, 2023). "In the study of prognostic‐related gene expression, breast cancers showed considerably lower levels of the pyroptosis pathway effector proteins caspase 1, IL‐1β, and GSDMD compared with nearby normal tissue." (PMID 37752941, 2023). "Taxol and cisplatin were shown to induce pyroptosis through the GSDMD/caspase-1 pathway in nasopharyngeal carcinoma and breast cancer, respectively." (PMID 38007535, 2023). "Caspase-1 in parenchymal cells of the tumor was negatively correlated with tumor progression, and upregulation of IL-18 in immune-stromal cells of breast cancer tissues is a promising prognostic biomarker and a potential immunotherapy target." (PMID 38031068, 2023). "Cisplatin induced anti-breast cancer effects at least partly by activating MEG3/NLRP3/caspase-1/GSDMD pathway." (PMID 36936274, 2022). "Meanwhile, high expression of IL1β, IRAK1 and Caspase-1 is closely correlated with reduced overall survival and distant recurrence of breast cancer." (PMID 36230739, 2022). "The same authors recently determined that inflammasome components can be regulated by the P2Y2R activation and are involved in tumor progression evidencing that NLRP3 and caspase-1 mRNA levels were upregulated in radiotherapy-resistant breast cancer cells." (PMID 33840390, 2021). "The expression of the inflammasome components, such as IL1B, IL18, NLRP3, PYCARD, and CASP1, is significantly up-regulated in most types of breast cancer compared to that in normal tissues." (PMID 33686176, 2021). "CASP1 is the component of the inflammasome that can induce pyroptosis and inhibit angiogenesis and migration of tumor cells (such as lung cancer, breast cancer, and endometrial cancer)." (PMID 34026619, 2021). "In silico meta-analysis of the expression of the genes CASP1, NLRP3 and IL-1β in breast cancer exhibited an association with prolonged overall survival." (PMID 33840390, 2021). "According to our observations, treatment with inhibitor of NLRP3 inflammasome or caspase-1 (MCC950 or Ac-YVAD-cmk) showed to inhibit breast cancer cells growth in MCF-7 and T47D breast cancer cells." (PMID 32155890, 2020).
breast cancer (continued). "NK cells infiltrating the mammary tumors of Caspase-1 KO were larger (according to FSC parameters) than those infiltrating WT mice, a feature which is commonly associated with a stronger activation status." (PMID 33042810, 2020). "To establish the effect of BRCA1 on inflammasome activation in mammary cells, we analyzed IL‐1β secretion and caspase 1 activation in MCF10A cells with detectable inflammasome‐associated components, compared to several breast cancer cell lines." (PMID 32195105, 2020). "Several studies have found that the DHA can trigger caspase-1 and GSDMD activation to cause pyroptosis in breast cancer cells, and enhance the secretion of IL-1β." (PMID 32182796, 2020). "P73 and, more particularly, Tap73, a constitutively active p73, is able to increase the transcription of IL1B and CASP1 in lung and breast cancer cells, allowing these cells to produce IL-1β." (PMID 32635472, 2020). "We demonstrated here that breast cancer cells can present caspase-1 activation, and once activated, caspase-1 can process pro-IL-1β and induce its secretion." (PMID 29386662, 2018). "Recently, it has been reported that caspase-1 mRNA expression was decreased in breast cancer tissues compared with tumor-adjacent normal tissues." (PMID 30042341, 2018). "The clinical database cBioPortal showed a correlation between the low expression of caspase-1 in the primary tumor and the poor survival of patients with breast cancer." (PMID 30042341, 2018). "Then, we examined the expression of TAM hallmarks in peritoneal macrophages derived from caspase-1−/− mice, cocultured with the mouse mammary tumor cell line 4T1." (PMID 28974683, 2017). "Also, nobiletin 59, a methoxy flavone, has pyroptotic induction efficacy against breast cancer through caspase-1/GSDMD/NLRP3 activation." (PMID 39316325, 2025). "In addition, according to a previous study, the caspase-1 gene in breast cancer tissues was significantly decreased compared with the adjacent normal tissues." (PMID 38031068, 2023). "Additionally, docosahexaenoic acid (DHA) has been proven to trigger MDA-MB-231 breast cancer cell pyroptosis via the caspase-1/GSDMD pathway, inducing IL-1β secretion, translocation of HMGB1 to the cytoplasm, and pore formation in the cell membrane." (PMID 38016064, 2023). "However, in human monocytes, the priming step alone is sufficient to mediate CASP1 activation and IL-1β release.Primary and metastatic mammary tumors are promoted by IL-1 signaling." (PMID 37300757, 2023). "Caspase-1 specifically cleaves PPARγ in breast cancer cells." (PMID 37004014, 2023). "CASP1 gene is identified as a prognostic factor for breast cancer, hepatocellular carcinoma, and pancreatic cancer, and it may influence tumor checkpoint inhibition by assisting T‐cell immunity regulation." (PMID 35574984, 2022). "In addition, caspase‐1 mRNA expression was found to be significantly decreased in the breast cancer tissues of patients, and treatment with a caspase-1 inhibitor markedly increased the proliferative and invasive abilities of MDA‐MB‐231 cells." (PMID 35256749, 2022). "Consistently, CASP1 is a prognostic factor as well as therapeutic target in breast cancer." (PMID 34589498, 2021). "detected the expression level of caspase-1, IL-1βand GSDMD, and they found that the expression of pyroptosis-related proteins were inversely correlated with the tumor grade, tumor size, clinical stage, death risk of breast cancer tissues." (PMID 34381721, 2021). "Interestingly, bone marrow chimeric mouse experiments demonstrated that caspase-1-expressing immune cells promote mammary tumor progression." (PMID 33042810, 2020). "Similarly, radiotherapy-resistant breast cancer cells secrete ATP, which in turn associates with its receptor P2Y2R on the cancer cell surface to induce caspase-1 activation and IL-1β release." (PMID 32635472, 2020). "The low expression of caspase-1 could be a new prognostic biomarker for early relapse in HER2-positive breast cancer." (PMID 30042341, 2018).